SMAD2 (SMAD family member 2)
Diseases named in the same sentence as SMAD2 in open-access papers (continued):
Sharing a sentence is not in itself a finding about the gene and the disease.
cancer (continued). "Moreover, we saw the loss of differentially transcript pairs of cancer hallmark genes including SMAD2 and AKT1 in all HCT116KO." (PMID 35552415, 2022). "The hotspots include two AA residues, i.e. P305 and R321 mutated 3 and 4 times, respectively, and the nonsense mutation p.S464Ter truncating the protein by five AAs, which is the most common SMAD2 mutation (13 occurrences in cancers such as COAD, STAD, and BRCA)." (PMID 33406242, 2021). "Interestingly, while TGFβs and Activins activate the same Smad pathway (Smad2/3), TGFβs autocrine mechanisms have been much more frequently described to be implicated in cancer progression than Activins, highlighting a singularity of Group 3 MBs." (PMID 31328883, 2019). "Loss of Smad2 and Smad4 indicated death outcome in cancer patients." (PMID 31238579, 2019). "In addition, Smad2 mutations are found in various cancers at a low frequency, whereas Smad3 mutations are rare and could be found only in colon cancers." (PMID 36549646, 2022). "Interestingly, SMAD2/3 inactivating mutations are scarce in cancers, notably in PDAC15,21,22." (PMID 36207615, 2022). "Indeed, within lung endothelial cells, we observed strong enrichment of cancer associated DNAm changes at binding targets of SMAD2/SMAD3, transcription factors that are known to be indispensable for vascular stability and integrity and which mediate TGF-beta induced EndoMT in cancer." (PMID 32883324, 2020). "Both substances contribute to stimulate CAF endoglin expression and therefore negatively modulate the TGFβ1/SMAD2/3 pathway in cancer cells by decreasing extracellular TGFβ1 levels." (PMID 40384860, 2025). "The expression of Smad2/3 was observed mainly in CAFs in 144 cases (41.0%) and on cancer cells in 316 (90.0%) cases." (PMID 39941916, 2025). "The Smad2/3-positive cancer cell group (n = 144) was significantly correlated with a high relapse rate (p = 0.032), a high advanced stage (p = 0.049), and periostin positivity (p < 0.001)." (PMID 39941916, 2025). "We investigated the impact of SMAD2 linker phosphorylation (pSMAD2L) on overall and disease-free survival, signal transduction, as well as cancer-related processes in non-small cell lung cancer (NSCLC)." (PMID 40319202, 2025). "Given that Smad2/3 activation is associated with the expression of MMP2, a key mediator of cancer metastasis, we examined MMP2 levels and found that AML-exos upregulated MMP2 expression in Thp-1 cells, which was reversed by ITD1." (PMID 41020812, 2025). "KIN17 is also linked to cancer cell proliferation, migration, invasion, and cell cycle control through pathways such as p38 MAPK, NF-κB–Snail, and TGF-β/Smad2." (PMID 39859203, 2025). "We demonstrated that TGF‐β1 produced by ENG‐primed TGF‐β‐Smad2/3 autocrine signaling in myCAFs induced pEMT in apposed carcinoma cells in a paracrine fashion, resulting in the promotion of invasion and metastasis." (PMID 40644310, 2025). "Treatment strategies that target downstream signaling components or TGF-β, SMAD2, TNFα, and NFκB receptors are being researched to limit the spread of cancer." (PMID 39156270, 2024). "Wnt5a has been reported to induce EMT and cancer stem cells in OC via the TGF-β1/Smad2/3 and Hippo-YAP1/TAZ-TEAD pathways." (PMID 38191909, 2024). "Such Smad2 or Smad3 specificity downstream of TGFβ signaling has been reported in the context of other cancer-related mechanisms." (PMID 38201651, 2024). "Previous study has demonstrated that hispidulin treatment inhibits transforming growth factor-β1 (TGF-β1)-induced Smad2/3 signaling in cancer cell lines." (PMID 39770583, 2024). "If not inhibited by endogenous (e.g., Smad6 and Smad7) or pharmacological (e.g., galunisertib or SB-431542) agents, increased TGF-β-Smad2/3 signaling activity in cancer cells induce cancer cell migration and invasion." (PMID 39724753, 2024). "CITED2 is a crucial mediator of the HIF1A hypoxic response, which, in cancer, is indicated to serve as a co-activator of SMAD2/3 affecting TGF-β signaling." (PMID 38339304, 2024).
cancer (continued). "CDK9 was also found to interact with the chromatin reader KAP1 and the transcription factor SMAD2, in sustaining transcriptional programs involved in cancer maintenance." (PMID 38172923, 2024). "TGF-β receptor–regulated SMADs: SMAD2 and SMAD3, are ubiquitous and constitutive in normal cells in general, whereas their loss is frequently observed in various cancers." (PMID 38960622, 2024). "TGF-β signaling derived from cancer cells or stromal cells initiates the differentiation of fibroblasts into myofibroblasts by inducing SMAD2 activity and contributes to malignant progression, especially distant metastasis." (PMID 36418470, 2023). "Meanwhile, it has recently been suggested that the TGF-β/Smad2/3 signaling pathway plays significant roles in cancer metastasis and progression (Batlle and Massagué 2019)." (PMID 37249822, 2023). "TGF-β was recently discovered to induce EMT (epithelial-mesenchymal transition), a key mechanism of cancer cell migration and invasion, by activating the Smad2/3 signaling pathway in FLSs." (PMID 36845163, 2023). "Mutations in the SMAD2, SMAD3, and SMAD4 genes are associated with cancers of the intestine, pancreas, or appendix." (PMID 37509254, 2023). "Together with two Reactome pathways (SMAD4 MH2 Domain Mutants in Cancer and SMAD2/3 MH2 Domain Mutants in Cancer), two KEGG pathways were related to pathways in cancer." (PMID 36959830, 2023). "We further found that the protein levels of TGFβ1 and its downstream proteins, including p-TGFBR1, p-Smad2/3, Smad2-4 and the TGFβ-responsive gene SERPINE1 (encodes PAI-1), were elevated after coculturing in cancer cells." (PMID 37705745, 2023). "SMAD2 plays different roles in different stages of cancer by regulating various biological processes." (PMID 36969909, 2023). "It was reported that miR-145 regulated different targets, including MUC13, TGF-β receptor and SMAD2, and slowed pancreatic cancer progression by impeding the proliferation, migration, and invasion of cancer cells." (PMID 38139352, 2023). "On the contrary, WNK1-activated OSR1 can phosphorylate Smad2/3 at residues Thr-220/179 and enhance their activity in cancer cells, which activates pro-EMT transcription factors and further promotes the expression of TGF-β1 in an autocrine manner." (PMID 36123332, 2022). "On the other hand, the protein levels of TGF-β, SMAD2/3, TGFBR1, and pSMAD1/5/9 in cancer stromal cells were positively associated with FOXP3+ T cell infiltration but negatively associated with CD8+ T cell infiltration." (PMID 36458816, 2022). "The inhibition of SMAD2 protein in the highly glycosylated signaling pathway stimulated by receptor TMEM123 can regulate the anti-apoptosis ability of cancer cells." (PMID 35164166, 2022). "Mechanistically, cancer cell-secreted TGF-β1 activated CAFs to induce THBS2 expression through the Smad2/3 pathway." (PMID 35547750, 2022). "Drugs targeting TGF-β-SMAD2/3 pathway were proven to have suppressive effect on the growth and invasion of cancer cells." (PMID 36313180, 2022). "As a member of an E3 ligase NEDD4 family, NEDD4L not only targets membrane proteins including ion channels and transporters, but also triggers the degradation of certain proteins involved in cancer signaling pathways such as Dvl2, SMAD2, and SMAD7." (PMID 36618071, 2022). "Indirect exposure of cancer cells to platelets through a transwell membrane activated Smad2/3 phosphorylation." (PMID 35626102, 2022). "TGF-β is a key inducer of the EMT, which is an important step in cancer progression, and Smad2/3 activation plays a crucial role in the EMT." (PMID 35580109, 2022). "Direct platelet exposure increased PD-L1 by both NF-κB and Smad2/3 signaling pathways in cancer cells, but indirect exposure to platelets increased PD-L1 mainly through TGFβR1/Smad signaling." (PMID 35626102, 2022). "We herein provide evidence of a SMAD2/3 oncogenic effect in response to TGF-β1 in SMAD4-null human PDAC cancer cells." (PMID 36207615, 2022).
cancer (continued). "To next evaluate the impact of SMAD2 or SMAD3 modulation on the invasive properties of cancer cells in hypoxia, we compared the capacity of HT-1080 and MDA-MB-231 knockdown cells to produce invadopodia under normoxic versus hypoxic conditions." (PMID 35681731, 2022). "We performed a clustering analysis based on eight cancer-associated molecules including HER2, c-Met, and p-Smad2 using the protein expression revealed by our immunohistochemical study of the patients’ and TCGA cases." (PMID 35650563, 2022). "This suggests that SSP1 and MMP9 are downstream target genes of the HOXB9/TGFβ/Smad2 pathway in the regulation of cancer metastasis." (PMID 34247196, 2021). "In particular, TβRI, TβRII, SMAD2, and SMAD4 are frequently mutated, deleted, or attenuated (gene/loss of heterozygosity/expression) in certain cancer subtypes." (PMID 33418880, 2021). "We also found that CaA attenuated cancer stem cell-like properties through the epigenetic regulation of the transforming growth factor (TGF)β–mothers against decapentaplegic homolog 2 (SMAD2) signaling pathway." (PMID 34395254, 2021). "There are direct pieces of evidence related to positive regulation of SMAD2 by lncRNAs to promote cancer." (PMID 33511320, 2021). "One previous study reported that GO activated TGF-β receptor/SMAD2/3 signaling to trigger new metastases of human cancer cells." (PMID 34298943, 2021). "We also confirmed the common occurrence of deleterious mutations in SMAD4 and further characterized the specific hotspot mutations in SMAD4, SMAD2 and DICER1, the last group of which were previously reported mostly in childhood cancers." (PMID 33406242, 2021). "During this study, we demonstrated that overexpression of transcription factor DLX2, activation of Smad2/3 signaling, and increased expression of betacellulin were observed in A549 cancer cells surviving the fractionated irradiation." (PMID 33924205, 2021). "Seemingly, SMAD2 and lncRNAs promote each other to enhance proliferation and metastasizing ability of cancer cells." (PMID 33511320, 2021). "TGFβ has been shown to promote cancer cell growth through regulating SMAD2/3 phosphorylation upon binding with its receptor." (PMID 34709754, 2021). "We further demonstrate that JMJD3 regulates TGF-β-induced EMT through a syntenin-TβR1 complex, subsequent activation of Smad2/3, cancer cell migration, and invasion." (PMID 33637682, 2021). "Their findings revealed the important role of the p-SMAD2/3 pathway in hepaCAM-induced apoptosis of cancer cells, and provided valuable insights for current and future clinical trials of Ad-hepaCAM and p-SMAD2/3." (PMID 35174173, 2021). "In the other two most prominent networks, the link to cancer is more indirect for the respective genes although the score of their relevance to CRC is basically identical to that of SMAD2/AKT and CDKN1A." (PMID 34288395, 2021). "This process includes the induction of Smad2/3 phosphorylation, the increase of Smad2/3 transcriptional activity, the expression of up-regulated Snail and Slug, thus promoting cancer cell migration and invasion." (PMID 34006286, 2021). "By contrast, Smad2 can contribute to TGF-β1-induced EMT, and the overexpression of constitutively active Smad2 increases EMT in cancer cells." (PMID 34947978, 2021). "Among EMT-related markers, activated SMAD2 represents a critical molecule that can accelerate cancer metastasis." (PMID 34386414, 2021). "On the another hand, HNK can block the crosstalk between cancer cells and nerves by suppressing the activating of SMAD2/3 signaling." (PMID 34671554, 2021). "It is worth highlighting that SMAD2/3 translocation can be blocked by mTORC1 inhibitors such as Everolimus, which is a therapeutic agent for PTEN-deficient cancers." (PMID 34638474, 2021).
cancer (continued). "A recent study showed that in gastric cancer, TGF-β1 secreted by MSCs activated the SMAD2/3 pathway and supported cancer progression through the lncRNA MACC1-AS1/miR-145-5p/fatty acid oxidation (FAO) axis in cancer cells." (PMID 34736460, 2021). "P234 is an antagonist of KiSS1, a downstream target of the canonical TGFβ/SMAD2 pathway in this cancer type." (PMID 33498521, 2021). "Subsequently, we revealed that CAFs secrete TGF-β1 to upregulate the expression of ATF4 in PDAC cells via the SMAD2/3 pathway and induce cancer progression, cancer stemness, and gemcitabine resistance." (PMID 33782384, 2021). "An inverse correlation between SMURF2 expression and phosphor-SMAD2 levels has also been observed in cancers." (PMID 33418880, 2021). "To date, the exact functions and regulatory mechanisms of SMAD2 in cancer are complicated and not fully understood." (PMID 32226309, 2020). "We confirmed the same effect in HPMCs that had been cultured with malignant ascites; the expression of αSMA and phospho‐SMAD2 were seen to decrease after treatment with RI." (PMID 31904865, 2020). "Consistent with increased BMP-mediated Smad2/3 signaling during cancer progression, BMP signaling through Smad3 occurs preferentially in transformed cells and facilitates cancer cell invasion." (PMID 33266416, 2020). "PFN2 is an epigenetic regulator of SMAD2/3 (Mothers against decapentaplegic homolog 2/3), which in turn has been shown to promote metastasis in cancer cells." (PMID 32183695, 2020). "Conversely, Smad2 and Smad4 showed inverse correlation to cancer-specific death (p = 0.003, and p = 0.022, respectively)." (PMID 31238579, 2019). "An exploratory analysis between CNV in RD samples and DFS revealed cancers bearing a copy gain of a region near SMAD4 on chromosome 18q were associated with poor prognosis, likely through upregulation of SMAD2." (PMID 31383035, 2019). "SMAD family member 2 (SMAD2) is a key element downstream of the transforming growth factor beta (TGF-β) signaling pathway that regulates cancer metastasis by promoting the epithelial-mesenchyme transition (EMT)." (PMID 31762811, 2019). "High Smad4, as well as Smad2 staining, indicates less aggressive tumors and longer cancer-specific survival." (PMID 31238579, 2019). "High TGF-β1 correlated directly, while Smad2 and Smad4 correlated inversely to cancer-specific death (p = 0.043, p = 0.003, and p = 0.022, respectively)." (PMID 31238579, 2019). "By extending the bridges of our sub-network with the literature survey results, we confirmed the oncosuppressor model of miR-148a through inhibition of cancer stemness by targeting SMAD2 in HCSC, AKT2 and KLF4." (PMID 30944375, 2019). "A previous study showed that silencing SMAD2 restrained TGF-β-induced EMT andcell invasion, indicating a therapeutic role for SMAD2 inhibition in cancer." (PMID 31762811, 2019). "This dual role of TGF-β/Smad2 pathway renders its comprehension as a possible prognostic moderator in cancer more difficult." (PMID 31387321, 2019). "Neuropilin-1 (NRP1), a TGF-β co-receptor expressed on the membrane of cancer cells, is known to enhance the canonical SMAD2/3 signaling in response to TGF-β." (PMID 31202261, 2019). "SMAD2 has been proven to be targeted and downregulated by various miRNAs such as miR-132 27, miR-27a 28, and miR-323-3p 29 in regulating multiple cancers." (PMID 31762811, 2019). "Immunohistochemistry (IHC) and immunofluorescence staining for CD133 as well as other cancer-associated proteins, including cytokeratin 19, TGF-β1, p-Smad2 and epithelial–mesenchymal transition (EMT) markers S100A4, E-Cadherin and Vimentin were analyzed." (PMID 29510695, 2018).
cancer (continued). "Conversely, anti-miR inhibition of miR-218 in CM-producing MDA-231-bone cells led to reduction of SMAD2/3 phosphorylation in cancer cells and de-repression of SMAD2/3 signaling in preosteoblasts at the 2-h time point." (PMID 30348200, 2018). "It has been shown that TGFβ1 can increase VEGF-C expression in certain cancer cells via Smad2/3 binding to the VEGF-C promoter region." (PMID 29995950, 2018). "Our study shows that secreted inhibin βA regulates SMAD2/3 signaling in cancer cells and osteoblasts in opposite directions, which is dependent on the absence or presence of inhibin α subunit." (PMID 30348200, 2018). "Previous publication indicated that efficacy of LY correlated with pretreatment expression of TGFBRI mRNA and p-SMAD2 protein expression in cancer PDX models." (PMID 30087253, 2018). "The results suggest that Smad2/3 and Smad4 control cancer spherical cell self-renewal by promoting CSC sphere proliferation and preventing CSC sphere differentiation." (PMID 28415588, 2017). "There was a significant reduction of nuclear phospho-Smad2/3 in cancer cells when mice were treated with halofuginone, showing a decrease of TGF-β signaling activity." (PMID 29156807, 2017). "Halofuginone decreased immunostaining of phospho-Smad2/3 and phospho-Smad1/5/8 in cancer cells in vivo." (PMID 29156807, 2017). "Next, we studied the TGF-β–induced phosphorylation of Smad2 and 3 proteins in cancer cells treated with halofuginone at different time points (1, 4 and 12h)." (PMID 29156807, 2017). "In order to investigate the effect of cancer cells on SMAD2/3 and its phosphorylated form, a western blot assay was performed on hASCs cultured alone and with MCF7 and SAOS2 at 7, 14 and 21 days." (PMID 28102844, 2017). "Smad2, which is regarded as a suppressor of cancer, has been observed inhibited in various types of cancer." (PMID 28881698, 2017). "In cyclin D1-overexpressing spherical cancer cells, Smad2/3 phosphorylation and the total level of Smad4 were enhanced, as shown by Western blots and flow cytometry." (PMID 28415588, 2017). "Double immunofluorescence staining further showed that B7-H4 is coexpressed with EMT-related markers, such as p-Smad2/3, Snail and Vimentin, in carcinoma cells." (PMID 29190910, 2017). "As a result of restoring the network state in each cancer progression stage, we have identified different sets of a minimal number of control nodes including beta-arrestin, P115RhoGEF, Smad2/4, ERK and Snail." (PMID 27765040, 2016). "For example, mutations in genes such as PTEN, SMAD2, TGFB2, and SRC implicated in epithelial-mesenchymal transition, metastasis, and cancer progression, were enriched in more aggressive groups while the other genes clustered in the less aggressive groups." (PMID 28007036, 2016). "The mouse cancer cell lines also expressed higher levels of TGFβ pathway downstream effector phosphorylated Smad2 or transcription factors Slug and Snail." (PMID 27602775, 2016). "It has been shown that PIAS1 modulates activation of Smad2/4 complex and further promotes Smad2/4 mediated proliferation inhibition observed in some cancer cells." (PMID 27553600, 2016). "Collectively, these data suggested that EGF induced EMT and cancer cell migration through ERK1/2-phospho-Smad2/3-Snail signaling pathway." (PMID 27829223, 2016). "Smad2 is a key element downstream of the TGF-β signaling pathway to regulate cancer metastasis by promoting epithelial to mesenchymal transition and maintaining the cancer stem cell (CSC) phenotype." (PMID 25980495, 2015). "E-cadherin is expressed by most epithelial tissues, and certain proteins expressed in cancer cells are also related to E-cadherin, such as Snail, Smad2, and Smad3." (PMID 26373288, 2015). "It has been shown that Smad2 is upregulated in CRC cancer tissue as compared to normal colorectal mucosa." (PMID 25980495, 2015). "It has been shown that Smad2 contributes to cancer initiation, invasion, metastasis and CSC self-renewal." (PMID 25980495, 2015).